EDNRA (endothelin receptor type A)
Diseases named in the same sentence as EDNRA in open-access papers (continued):
Sharing a sentence is not in itself a finding about the gene and the disease.
Obesity (10 papers, 2014 to 2025). Accumulation of substantial excess body fat. "In our previous analyses of this study population, genetic polymorphisms of EDNRA revealed a significant interaction with regular exercise or obesity on IMT." (PMID 32214403, 2020). "Our previous study showed that EDNRA gene rs1395821 significantly interacted with regular exercise and rs5333 with obesity on IMT." (PMID 32214403, 2020). "We found gender, regular exercise, and obesity significantly interacted with SNPs in the EDNRA gene, and gender interacted with SNPs in the EDN1 gene to influence carotid IMTs in the Han Chinese participants of the TCHS study." (PMID 26040574, 2015). "After multivariate adjustment, the effects of interactions between EDNRA SNPs rs1395821, rs1878406, and rs5333 with gender as well as EDNRA SNP rs5333 with obesity on CCA IMT were observed." (PMID 26040574, 2015). "The gene-gender, gene-exercise, and gene-obesity interactions for EDNRA and EDN1 SNPs on carotid IMT were explored." (PMID 26040574, 2015). "This study first reported significant interactions of EDNRA and EDN1 polymorphisms with gender, regular exercise, and obesity on carotid IMT in Han Chinese participants." (PMID 26040574, 2015). "Genetic variants in NO synthase and EDN isoforms and its receptors (EDNRA and EDNRB) appear to account for important components of the variance in ED, particularly when concurrent risk factors such as obesity exist." (PMID 24410812, 2014). "Still, further studies will be necessary to genotype other important variants underlying the EDNRA and EDN1 signals, and to elucidate the mechanisms with which gender, regular exercise, and obesity modify the effects of these polymorphisms on carotid IMT in Han Chinese." (PMID 26040574, 2015). "After multivariate adjustment, the effects of interactions between EDNRA and EDN1 gene with gender, obesity, and exercise were observed." (PMID 26040574, 2015). "Therefore, in our study we examined the associations of five SNPs in EDN1 and EDNRA genes with carotid IMT in a Han Chinese sample from the Taichung Community Health Study (TCHS), and evaluated their interaction effects by gender, regular exercise, and obesity status." (PMID 26040574, 2015). "Furthermore, the minor allele (G) of EDNRA SNP rs5333 decreased bulb and CCA IMT levels in individuals without regular exercise or obesity whereas the minor allele (G) of EDNRA SNP rs1395821 increased bulb IMT level in individuals without regular exercise." (PMID 26040574, 2015).
coronary artery disease (9 papers, 2012 to 2025). "It is of note that a functional genetic variant of EDNRA was also associated with other vascular diseases including coronary artery disease, intra cranial aneurysm and ischemic stroke." (PMID 26488411, 2015). "For example, the gene EDNRA, a known target of aspirin, is shared by the multimorbidity of I20 (Angina pectoris) and I25(Chronic ischaemic heart disease), and we find that 65% of the people suffering from both diseases report usage of aspirin in the UKB." (PMID 34225788, 2021).
gastric cancer (9 papers, 2021 to 2025). A primary or metastatic malignant neoplasm involving the stomach. "In addition, high expression of EDNRA in gastric cancers is associated with the advanced STAD pathological grade and T classification." (PMID 35517422, 2022). "Our results provide valuable insights into EDNRA's role in gastric cancer progression but are limited in capturing how EDN signalling evolves over time during gastric cancer progression." (PMID 40245183, 2025). "EDNRA signalling interacts with multiple downstream effectors, potentially offering stronger therapeutic targets for gastric cancer treatment." (PMID 40245183, 2025). "This dual pathway activation explains ABT‐627's anti‐proliferative effects, suggesting its potential therapeutic application in gastric cancer treatment, particularly in cases with elevated EDNRA expression." (PMID 40245183, 2025). "EDNRA protein levels closely mirrored the mRNA expression patterns, confirming elevated expression in gastric cancer cell lines with particularly strong signals in NCI‐N87 and MKN‐28 cells." (PMID 40245183, 2025). "EDNRA, previously underexplored in this context, showed remarkable upregulation across diverse gastric cancer cell lines." (PMID 40245183, 2025). "Using gastric cancer cell lines, we confirmed that the inhibition of EDNRA indeed downregulated cell proliferation and upregulated apoptosis." (PMID 40245183, 2025). "The functional validation of EDNRA signalling demonstrates its significant role in gastric cancer progression." (PMID 40245183, 2025). "EDNRA showed marked upregulation in all gastric cancer cell lines examined (MKN‐45, NCI‐N87, MKN‐28 and HGC‐27) compared to normal gastric epithelial GSE‐1 cells, with the highest expression observed in NCI‐N87 and MKN‐28." (PMID 40245183, 2025). "In conclusion, EDNRA functions as both a regulatory factor and therapeutic target, offering a promising therapeutic avenue for gastric cancer intervention." (PMID 40245183, 2025). "Wei 11 showed that EDNRA is overexpressed in gastric cancer cells compared with normal gastric cells (P < 0.01)." (PMID 35517422, 2022). "The latest research suggests that high EDNRA expression was correlated with advanced gastric cancer." (PMID 35517422, 2022). "EDNRA is the downstream target gene of microRNA-200C, microRNA-200C knockdown, showed that EDNRA can significantly inhibit the proliferation and invasion ability and promote apoptosis in gastric cancer cells." (PMID 35517422, 2022). "Furthermore, studies have demonstrated that in aggressive tumors such as bladder and gastric cancers, EDNRA expression is influenced by the upregulation of the STAT3 signaling pathway." (PMID 41515956, 2025). "These strong correlations suggest that EDNRA signalling may interact with immunostimulatory pathways, potentially enhancing the tumour activation within the microenvironment in gastric cancer." (PMID 40245183, 2025). "However, the specific mechanism through which EDNRA regulates the occurrence and development of gastric cancer, and its clinical and immune value in gastric cancer, require further clarification." (PMID 35517422, 2022). "Conversely, pharmacological inhibition of EDNRA using ABT‐627 suppressed both NCI‐N87 and MKN‐28 gastric cancer cells proliferation." (PMID 40245183, 2025). "In the HPA database, the protein expression of the four model genes EDNRA, SPARC, THBSI, and VCAN was higher in gastric cancer tissues compared with normal tissues." (PMID 39040110, 2024). "Results of the ROC curve showed that ADAM12 and EDNRA, and CPNE8 had high value in the diagnosis of gastric cancer." (PMID 34663825, 2021). "Similarly, the inhibition of EDNRA by ABT‐627 reduced growth in both NCI‐N87 and MKN‐28 gastric cancer cells significantly within 96 h." (PMID 40245183, 2025). "EBV also uses GPCR signaling, such as EDNRA, a common DEG in gastric cancer." (PMID 39228892, 2024). "It suggested that ADAM12, EDNRA, and STC1 had high value in the diagnosis of gastric cancer." (PMID 34663825, 2021).
gastric cancer (continued). "Additionally, the study explored the ET-1/endothelin receptor type A (ETAR) axis, finding that inhibiting the ERK1/2 pathway downregulated ET-1 and FOX01, suggesting ET-1’s role in promoting cell proliferation, migration, and anti-apoptosis in gastric cancer through the ET-1/ETAR axis." (PMID 39452747, 2024). "However, the role of EDNRA in gastric cancer was not studied enough." (PMID 35517422, 2022).
glaucoma (9 papers, 2007 to 2024). Increased pressure in the eyeball due to obstruction of the outflow of aqueous humor. "Many more important gene variants have recently been associated with glaucoma risk, such as apolipoprotein E (APOE), endothelin receptor type A gene (EDNRA), IL-1α, methylenetetrahydrofolate reductase (MTHFR), and beta-adrenergic receptors." (PMID 17563722, 2007). "Therefore, it is possible that aberrant EDN signaling via mural cell-EDNRA contributes to reduced retinal blood flow in glaucoma, which could in turn perpetuate neurodegeneration via JNK-JUN signaling." (PMID 32980857, 2020). "Given the importance of vascular compromise in glaucoma, it is possible that EDNRA-induced vasoconstriction and its sequelae damages the blood-brain barrier and plays a role in neurodegeneration in response to EDN1 ligand and in glaucoma." (PMID 35429992, 2022). "Future work should elucidate the role of EDNRA and hypoxia in mediating RGC death after EDN1 insult and in models of glaucoma." (PMID 32980857, 2020). "Multiple cell types in the retina and optic nerve express EDNRA and EDNRB and thus could respond to EDN ligands in the context of glaucoma." (PMID 35429992, 2022).
bladder cancer (8 papers, 2013 to 2023). "High expression of EDNRA is associated with metastasis and poor outcome in patients with advanced bladder cancer." (PMID 35631574, 2022). "EDNRA overexpression was shown to be associated with metastasis and poor outcome in advanced bladder cancer patients." (PMID 33465047, 2021). "Several studies have reported that EDNRA was closely related to the occurrence and development of some tumors, including bladder cancer, renal cell carcinoma (RCC), osteosarcoma, and ovarian cancer 7-10." (PMID 35517422, 2022). "The latest research suggests that EDNRA was one of immune-related genes and closely related to tumor infiltration of macrophages in bladder cancer." (PMID 35517422, 2022). "EDNRA was significantly increased in bladder cancer and is related to metastasis and poor prognosis in cystic cancer patients." (PMID 34663825, 2021).
colorectal cancer (8 papers, 2020 to 2024). A primary or metastatic malignant neoplasm that affects the colon or rectum. "In fact, incubation of human colorectal adenocarcinoma Caco2 cell line with 10 μM HT increased DNA methylation, leading to the repression of the crucial colorectal cancer promoter endothelin receptor type A (EDNRA)." (PMID 38540115, 2024). "An antagonist of EDNRA, macitentan, has been shown to sensitize colorectal cancer cells and brain metastases to chemotherapy, and it is plausible that it may help to overcome the resistance mechanisms in this TNBC cluster." (PMID 38999963, 2024).
diabetic nephropathy (7 papers, 2013 to 2025). "EDNRA itself has been implicated in diabetic kidney disease, where a study found that certain polymorphisms in the EDNRA and EDN1 gene acted protective against the development of the disease." (PMID 38153746, 2023).
cardiac hypertrophy (6 papers, 2014 to 2023). "It contributes to a reduction in cardiac output, the stimulation of cardiac hypertrophy, and fibroblast proliferation by activating two G-protein–coupled receptors: endothelin receptor type A (ETA) and endothelin receptor type B (ETB)." (PMID 31766450, 2019).
COVID-19 (6 papers, 2022 to 2025). A disease caused by infection with severe acute respiratory syndrome coronavirus 2. "Endothelin receptor type A (ETAR) auto-antibodies were also more frequent in severe COVID-19 patients." (PMID 36519165, 2022). "Our prior work published in this journal demonstrated significantly increased autoantibodies against the GPCR angiotensin II receptor type 1 (AT1R) and endothelin receptor type A (ETAR) in patients with COVID-19 with unfavorable disease course compared to mild disease." (PMID 37622126, 2023).
myocardial infarction (6 papers, 2012 to 2025). Gross necrosis of the myocardium, as a result of interruption of the blood supply to the area, as in coronary thrombosis. "VCAM-1 supports angiogenesis, EDNRA mediates induction of CDH2 and VEGF by EDN, thereby contributing to tissue restoration after myocardial infarction, while BMPER is known to play an important role in osteogenesis." (PMID 37686058, 2023).
asthma (5 papers, 2007 to 2025). "Furthermore, multiple genes, such as ATF3, activation‐induced cytidine deaminase (AICDA), thymic stromal lymphopoietin (TSLP), and endothelin receptor type A (EDNRA), are associated with asthma." (PMID 37385291, 2025). "In future research, we will further explore the relationship between miR‐27a‐3p and AICDA, TSLP, EDNRA, and other asthma‐related genes and their expression levels and clinical roles in the serum of children with BA." (PMID 37385291, 2025).
colon carcinoma (5 papers, 2013 to 2026). "For example, the depressed expression of EDNRA is associated with a better prognosis in colon cancer." (PMID 31500382, 2019). "Interestingly, lower expression of a number of genes (GREM1, LOX, TNFAIP6, CD36, and EDNRA) predicted better prognosis in both ovarian and colon cancers." (PMID 23536776, 2013). "It suggests that the hsa-mir-21-5p to COL5A2/OLR1, hsa-mir-135b-5p/hsa-mir-495-3p/hsa-mir-409-3p to COL5A2 and hsa-mir-224-5p/hsa-mir-21-3p/hsa-mir-135b-5p/hsa-mir-495-3p to EDNRA pathways may play substantial roles in regulation of the tumor immune microenvironment in colon cancer." (PMID 31500382, 2019). "Collectively, the expression pattern, prognostic effect, immune-inhibitory activity demonstrated the oncogenic effect of COL5A2, EDNRA, and OLR1 in colon cancer." (PMID 31500382, 2019). "Nevertheless, to our knowledge, inhibition of EDNRA or COL5A2 has not been tested for colon cancer treatment." (PMID 31500382, 2019).
glioma (5 papers, 2008 to 2024). A benign or malignant brain and spinal cord tumor that arises from glial cells (astrocytes, oligodendrocytes, ependymal cells). "Both AKT and JNK inhibition blocked EDN‐induced glioma cell migration, and AKT inhibition prevented EDNRA‐mediated migration of hepatocellular carcinoma cells." (PMID 31464372, 2019).
IgA nephropathy (5 papers, 2024 to 2025). "Sparsentan, a dual-acting antagonist for both the angiotensin II receptor type 1 and the endothelin receptor type A, has emerged as a promising therapeutic agent for the treatment of IgA nephropathy (IgAN)." (PMID 39872637, 2025).
melanoma (5 papers, 1998 to 2022). A malignant, usually aggressive tumor composed of atypical, neoplastic melanocytes. "A similar situation was observed in melanomas from patients, where EDNRA expression levels were also lower than EDNRB levels and were increased on treatment." (PMID 28606996, 2017). "Because we saw a correlation of AXL expression with EDNRA expression in the xenografts, we interrogated publicly available gene expression data, including the TCGA‐melanoma as well as two melanoma cell line datasets." (PMID 28606996, 2017). "In addition, the Gene Expression Omnibus (GEO) database (GSE78220) of melanoma patients was used to evaluate the role of EDNRA in PD-1/PD-L1 blockade." (PMID 35265193, 2022). "We could further confirm the mutual exclusion of MITF/EDNRB and AXL/EDNRA expression in a panel of melanoma cell lines." (PMID 28606996, 2017). "Thus, the neural crest origin, but de‐differentiated nature of AXL‐high melanoma cells might explain why they express preferentially EDNRA, while differentiation towards the melanocyte lineage, triggered by MITF expression, results in a switch to EDNRB expression." (PMID 28606996, 2017).
serous ovarian cancer (5 papers, 2015 to 2024). "Our data also indicated that both EDNRA and COL3A1 showed significant prognostic properties in patients diagnosed with high-grade serous ovarian cancer." (PMID 26100469, 2015).
alopecia (4 papers, 2016 to 2023). Hair loss usually from the scalp. "Here, we establish p.E303K in the gene encoding the endothelin receptor type A (ETAR/EDNRA) as a recurrent mutation causing mandibulofacial dysostosis with alopecia (MFDA), with craniofacial changes similar to those caused by p.Y129F." (PMID 36637912, 2023). "Recently, 2 missense mutations of EDNRA, p.Y1292.53F and p.E3036.32K, were identified as the cause of mandibulofacial dysostosis with alopecia (MFDA, MIM 616367)." (PMID 36637912, 2023). "Oro-oto-cardiac syndrome (OOCS) and mandibulofacial dysostosis with alopecia (MDFA; MIM 616367) are caused by variants in EDNRA (MIM 131243), although the variants affect EDNRA function differently." (PMID 35284927, 2022). "EDNRA encodes an endothelin receptor in which rare missense variants cause mandibulofacial dysostosis (OMIM:616367), where patterning defects of the hair follicle lead to alopecia." (PMID 35132056, 2022).
essential hypertension (4 papers, 2010 to 2023). Hypertension that presents without an identifiable cause. "Among them, AGTR1, AKT1 with puerarin, EDNRA with tanshinone IIA, MAPK14 with daidzein, MAPK8 with ursolic acid, and CHRM2 with cryptotanshinone all have a strong correlation with GJD in the treatment of primary hypertension." (PMID 36046450, 2022). "The research uncovered that the key active ingredients of GJD in managing primary hypertension are puerarin, tanshinone IIA, daidzein, ursolic acid, and cryptotanshinone, which are mainly expected to contain a regulatory function in conjunction with AGTR1, AKT1, EDNRA, MAPK14, MAPK8, and CHRM2." (PMID 36046450, 2022).
nasopharyngeal carcinoma (4 papers, 2009 to 2018). A carcinoma arising from the nasopharyngeal epithelium. "Endothelin receptors A and B (EDNRA, and EDNRB) have altered expression levels in multiple cancers, such as colorectal, bladder, prostate, and nasopharyngeal carcinomas, in addition to cervical cancer." (PMID 30020984, 2018).
breast tumor (3 papers, 2009 to 2026). "This will unravel in detail the inter-relationship between EDN3 expression loss and upregulation of EDN1/2 and EDNRA/B as well as its association with breast tumour progression." (PMID 19527488, 2009).
cystic fibrosis (3 papers, 2017 to 2022). Autosomal recessive disorder caused by pathogenic variants in the CFTR gene (cystic fibrosis transmembrane conductance regulator), which encodes a chloride and bicarbonate channel expressed in epithelial cells, and follow the diagnosis criteria. "DNA methylation was associated with pulmonary severity in three genes (HMOX1, GSTM3, and EDNRA) and with a polymorphic deletion that has a protective effect in cystic fibrosis at one gene (GSTM3)." (PMID 28289476, 2017). "This confirmation of the contribution of TGFB1 or EDNRA to CBAVD could point to another common link between cystic fibrosis and CBAVD." (PMID 32722328, 2020).
glomerulosclerosis (3 papers, 2021 to 2025). A hardening of the kidney glomerulus caused by scarring of the blood vessels. "The crosstalk signaling between podocyte dysfunction and depletion in glomerulosclerosis is mediated by Endothelin-1 (EDN1)/Endothelin Receptor Type A (EDNRA)-dependent mitochondrial dysfunction." (PMID 34576149, 2021).
ovarian tumors (3 papers, 2015 to 2017). "Future investigations EDNRA in ovarian tumors, where survival data is available, would elucidate its potential role identifying subpopulations of patients and direct treatment accordingly." (PMID 27600227, 2015).
pancreatic cancer (3 papers, 2012 to 2023). "EDNRA encodes the endothelin-1 receptor and has been associated with pancreatic cancer prognosis." (PMID 29422604, 2018). "The contributing genes to this pathway, e.g. CCKBR, CHRM5, EDNRA, LPAR1, SSTR2/3, and SCTR, have diverse functions in regulating the endocrine and exocrine functions of the pancreas, which are highly relevant to pancreatic cancer." (PMID 23056513, 2012).
renal fibrosis (3 papers, 2018 to 2025). A final common manifestation of a wide variety of chronic kidney diseases characterized by glomerulosclerosis and tubulointerstitial fibrosis. "Since Endotheli-1 (ET-1) and nitric oxide systems are important regulators of renal fibrosis we measured ET-1, endothelin receptor A (EDNRA), endothelial nitric oxide synthase (eNOS) and inducible nitric oxide synthase (iNOS) gene expression by real-time PCR." (PMID 30546836, 2018).